FOXP1 (forkhead box P1)
Diseases named in the same sentence as FOXP1 in open-access papers (continued):
Sharing a sentence is not in itself a finding about the gene and the disease.
cancer (continued). "Thus far, our findings indicate that circadian patterns of gene expression are disrupted in cachectic skeletal muscles in response to cancer that may be mediated, at least in part, via FoxP1-dependent upregulation of clock transcriptional repressors." (PMID 40349340, 2025). "However, transcriptional networks targeted by FoxP1 in skeletal muscles undergoing cancer-induced wasting remain largely unknown." (PMID 40349340, 2025). "Moreover, FOXP1 was reported to be a valuable predictor of outcomes in different types of cancer." (PMID 38279090, 2024). "FOXP1 might predict poor overall survival (OS) in patients with specific cancer types." (PMID 37953789, 2023). "In addition, FoxP1 is a crucial modulator of cancer‐induced skeletal muscle atrophy." (PMID 36564038, 2023). "Importantly, promoter analysis of target genes repressed by FoxP1 during cancer revealed strong enrichment of binding sites for MEF2—a family of transcription factors that activate muscle‐specific genes and are together required for muscle differentiation and regeneration." (PMID 33527776, 2021). "However, the expression patterns of FOXP1 vary in different types of cancers." (PMID 29934982, 2018). "Since Foxp1-Shq1 deletion and Pten loss cooperate together to promote murine prostate oncogenesis, we next asked whether combined loss of PTEN and FOXP1-SHQ1 locus genes were associated with worse outcome in human cancer." (PMID 29057879, 2017). "In univariate analysis, we found 17 significant genes, located on 3p14.1, 3q13.2, 17q12, and 18q22.1; these genes included cancer-related genes, such as FOXP1, GRB7, and NFATC1, indicating that altered expression of specific genes through CNAs could influence the clinical course of patients." (PMID 26465158, 2015). "We also found that FOXP1 directly modulated the expression of ABCG2, a membrane transporter that promotes the efflux of gemcitabine from cancer cells." (PMID 40169859, 2025). "In addition to mediating the cancer-induced disruptions to the normal rhythmic expression patterns of clock-controlled genes involved in oxidative metabolism, we show herein that skeletal-muscle FoxP1 was required for the gain in rhythmicity of gene programs linked to muscle wasting." (PMID 40349340, 2025). "For the analysis, we used next-generation sequencing with the Hot Spot Cancer Panel provided by Illumina Inc., San Diego, CA, USA, and an immunohistochemical analysis of FOXA1, FOXP1, and estrogen receptors." (PMID 36012038, 2022). "In a number of cancer types, including THCA, we observed that lower FOXP1, FOXP2 and higher FOXP3, FOXP4 levels in cancer tissues when compared with matched normal tissue." (PMID 36203616, 2022). "miR-1 targets several cancer-related molecules, such as Slug, PI3KCA, FoxP1, Pim-1, HDAC4, CCDN2, and CXCR4, indicating that miR-1-3p regulates the expression of several oncogenic pathways." (PMID 35804872, 2022). "FOXP1 functions in a histone deacetylase (HDAC)-dependent mechanism and FOXP1 knockdown confers partial protection against cancer-induced muscle atrophy." (PMID 36077789, 2022). "FOXP1 belongs to the subfamily P of the forkhead box (FOX) transcription factor family, which is involved in a wide range of cancers." (PMID 33372387, 2021). "Via Smad2/Smad3 and transforming growth factor β (TGF-β) signaling, increased FOXP1 expression restrained CD8+ T cells from proliferation and activation in cancer." (PMID 32719717, 2020). "Cytoscape analysis of gene network revealed important cancer pathways including hub genes at NFGR, MAPK3, and SMAD7 for OS, and hub genes at FOXP1, MAP2K5, FGFR1, and NOTCH2 for DFS." (PMID 31608231, 2019). "Therefore, we supposed that LINC01614 may impact cancer development by regulating FOXP1." (PMID 29934982, 2018).
cancer (continued). "In this study, in analogy with the molecular mechanism of RAG expression in B cells, we explored the regulatory mechanism of RAG expression in cancer cells by analyzing the transcription factors E2A, Ikaros, PAX5β, FOXO1, FOXP1 and NF-κB." (PMID 21655267, 2011). "Over-expression of E2A, FOXO1 or Foxp1 increased RAG expression, while RNA interference of E2A, FOXO1 or FOXP1 decreased RAG expression in the cancer cells." (PMID 21655267, 2011). "Furthermore, analysis of FOXP1 expressions across cancer types from the GEPIA2 and Human Protein Atlas datasets showed that FOXP1 was overexpressed in multiple cancer types, with PAAD displaying the most pronounced upregulation." (PMID 40169859, 2025). "Of the 673 FoxP1-dependent DEGs across all time points in skeletal muscle of KPC mice, 108 displayed FoxP1 binding within their promoter regions (74 upregulated and 34 downregulated), supporting these genes as direct FoxP1 targets in response to cancer." (PMID 40349340, 2025). "Thus far, interaction between FOXP1/3 and NFAT1/2 has been observed mainly in cancer or immune (T and B) cells." (PMID 39595620, 2024). "Forkhead box P (FOXP) TFs—FOXP1, FOXP2, FOXP3, and FOXP4—are involved in embryonic development, immune disorders, and cancer progression, but FOXP3’s targeting of CD4 + CD25+ regulatory T (Treg) cells and its dual role as an OCG or tumor suppressor in cancers are unclear and controversial." (PMID 38827026, 2024). "Three of these genes (RELN, IRS2, and FOXP1) have a known association with non-CRC digestive cancers and one (RRAS2) has a known association with non-CRC cancer." (PMID 37627102, 2023). "However, in previous studies, the FOXP1 protein was either located in the nuclei, or its subcellular location was not specified; nonetheless, cytoplasmic FOXP1 localization might play a large role in cancer cell biology because nuclear expression is characteristic of normal breast tissues." (PMID 29848352, 2018). "Nevertheless, our findings suggest immunohistochemistry for FOXP1/NRP1/cyclin D1 may be useful, in conjunction with family history, in selecting patients with basal cancers for BRCA1 screening." (PMID 26152113, 2015). "The expression of Cyclin D1, FOXP1, FIH-1, pan-ERβ, NRP1 and CD99, predicted to be regulated by BRCA1 specific miRNAs by computer prediction algorithms, was assessed via immunohistochemistry in a cohort of 35 BRCA1 and 52 sporadic basal-like cancers." (PMID 26152113, 2015). "Similarly, cancers that had invaded nearby organs had significantly lower levels of FOXP1 expression than those that had not (p < 0.05)." (PMID 38279090, 2024). "In addition, of all the 31 Onco/TSGs harboured sHyperMethyl and sHypoMethyl in their gene body, 7 genes (HOXD11, TAL1, HOXA9, PAX5, FOXP1, FOXO1, TERT) were reported to serve as potential DNA methylation-based biomarkers for non-invasive early cancer diagnosis." (PMID 37393582, 2023). "Our data further indicate that the muscle wasting phenotype induced by FoxP1 is mediated through an HDAC‐dependent mechanism, and that similar to treatment with HDAC inhibitors, knockdown of FoxP1 also confers partial protection against cancer‐induced muscle fibre atrophy." (PMID 33527776, 2021). "Although the expressions of FOXP1 and FOXQ1 mRNA were increased in cancer tissue, the difference was not statistically significant (P > .05)." (PMID 38608123, 2024).
neurodevelopmental disorder (33 papers, 2012 to 2026). A behavioral and cognitive disorder with onset during the developmental period that involves impaired or aberrant development of intellectual, motor, or social functions. "Mutations or deletions in the FOXP1 gene result in a neurodevelopmental disorder known as FOXP1 syndrome." (PMID 40672953, 2025). "FOXP1 haploinsufficiency causes FOXP1 syndrome, a neurodevelopmental disorder manifesting in autistic traits, ID, speech and language deficits and dysmorphic features." (PMID 35052467, 2022). "FOXP1 syndrome is a neurodevelopmental disorder caused by mutations or deletions that disrupt the forkhead box protein 1 (FOXP1) gene, which encodes a transcription factor important for the early development of many organ systems, including the brain." (PMID 33892622, 2021). "Fork-head Box P subfamily 1 (Foxp1) has been linked to neurodevelopmental disorders, suggesting that it may play a central role in various cognitive and social processes." (PMID 38280977, 2024). "More thorough phenotypic comparison studies between these distinct neurodevelopmental disorders and functional follow‐up would be required to uncover whether equivalent variants in FOXP1 and FOXP4 directly impact speech and language or whether they have an indirect effect on the function of FOXP2." (PMID 34260143, 2021). "Variants in ASD-associated genes (CHD8, FOXP1, and SHANK1) and genes linked to other neurodevelopmental disorders (CDH15, GATAD2B, and SHROOM4) were also detected." (PMID 40642607, 2025). "Increasing research evidence suggests the link between FOXP1 and neurodevelopmental disorders (NDDs), such as ASD and ID." (PMID 41156002, 2025). "Their detailed clinical presentation contributes important information to the understanding of the FOXP1-related neurodevelopmental disorder." (PMID 38891897, 2024). "The FOXP1-related neurodevelopmental disorder was described as a recognizable entity with a wide clinical spectrum in 2017." (PMID 38891897, 2024). "The FOXP1-related neurodevelopmental disorder was described as a recognizable entity with a wide clinical spectrum." (PMID 38891897, 2024). "FOXP1 plays a crucial role in coordinating signaling pathways related to neurogenesis and neurodevelopmental disorders, thereby impacting the generation of excitatory cortical neurons, especially in basal radial glial cells." (PMID 38491019, 2024). "In humans, a haploinsufficiency of FOXP1 leads to the FOXP1 syndrome, a neurodevelopmental disorder with prominent autistic features." (PMID 38255315, 2024). "Haploinsufficiency of the forkhead-box protein P1 (FOXP1) gene leads to a neurodevelopmental disorder termed FOXP1 syndrome." (PMID 29090079, 2017). "The FOXP1-related neurodevelopmental disorder is one of the most recently recognized NDDs." (PMID 38891897, 2024). "Mutations or deletions that disrupt the FOXP1 gene cause the autosomal dominantly inherited “intellectual developmental disorder with language impairment with or without autistic features” disease (OMIM#613670) or FOXP1-related neurodevelopmental disorder (or FOXP1 syndrome for short)." (PMID 38891897, 2024). "In addition, our results highlight the utility of next-generation sequencing in establishing an etiological basis for heterogeneous conditions such as neurodevelopmental disorders and providing additional insight into the phenotypic features of FOXP1-related syndrome." (PMID 37895307, 2023).
neurodevelopmental disorder (continued). "As there is increasing evidence that glia cell alterations play a role in neurodevelopmental disorders such as ID and ASD, we examined both striatal astrocytes and microglia in WT and Foxp1± animals." (PMID 40568906, 2025).
hematologic malignancies (6 papers, 2017 to 2025). "Our findings demonstrated that FOXP1 expression was dysregulated in several hematological malignancies and was associated with poor prognosis." (PMID 40672953, 2025). "As for hematological malignancies, however, FOXP1 plays an oncogenic role and is associated with malignant progression and a poor prognosis." (PMID 38279090, 2024). "Next, we assessed the prognostic value of FOXP1 expression in patients with hematological malignancies." (PMID 40672953, 2025). "Building on these previous findings, we aimed to further investigate the role of FOXP1 across hematologic malignancies." (PMID 40672953, 2025). "In conclusion, this study systematically investigated the role of FOXP1 across a spectrum of hematological malignancies and demonstrated that FOXP1 was a promising prognostic biomarker and a potential therapeutic target in AML and other hematological malignancies." (PMID 40672953, 2025). "Therefore, our data suggested that FOXP1 might serve as a potential prognostic biomarker in certain hematologic malignancies, particularly DLBCL and MM." (PMID 40672953, 2025). "We analyzed the correlation between FOXP1 expression levels and 29 TME signatures in hematological malignancies." (PMID 40672953, 2025). "In some hematological malignancies, miR34a is dysregulated and plays a role in the pathogenesis by repressing its target genes, such as SIRT1 and FOXP1." (PMID 28008152, 2017). "However, the clinical role of FOXP1 in hematologic malignancies has not been studied comprehensively." (PMID 40672953, 2025).
cardiovascular diseases (3 papers, 2022 to 2026). "Some experts have dedicated themselves to investigating the possible effects of FOXP1 on cardiovascular diseases, and they demonstrated that FOXP1 plays crucial roles in the regulation of cardiovascular remodeling and dysfunction." (PMID 35043753, 2022). "One possible target for treating cardiovascular diseases was FOXP1." (PMID 41596522, 2026).
heart disease (3 papers, 2019 to 2024). "Via transcription regulatory network analysis, we identified FOXP1, a core transcription factor in organ development, as a key downregulated factor in aged cardiomyocytes, concomitant with the dysregulation of FOXP1 target genes associated with heart function and cardiac diseases." (PMID 37084237, 2023).
infection (3 papers, 2011 to 2024). The state of being infected such as from the introduction of a foreign agent such as serum, vaccine, antigenic substance or organism. "To address this, we nucleofected Cas9/single-guide RNA (sgRNA) ribonucleoprotein (RNP) complexes targeting GATA3 or FOXP1 into HIV-GFP-infected primary CD4+ T cells at 1 week post infection." (PMID 38902848, 2024). "From the genes selected for validation, FOXP1 tended to be higher in parasitized rats offered the LP diet compared to the other infection-diet combinations, whereas expression data for two other candidate genes (GYG1 and AGR2) were not confirmed." (PMID 21698235, 2011). "Infection with the pri-miR-1-expressing virus silenced the validated miR-1 targets FOXP1 and MET." (PMID 33335978, 2020).
adenocarcinoma (2 papers, 2017 to 2021). A common cancer characterized by the presence of malignant glandular cells. "Foxp1-Shq1f/f;Ptenf/f tumors nonetheless retain expression of luminal markers such as CK8/18 as seen in human adenocarcinoma." (PMID 29057879, 2017).
blood cancers (2 papers, 2021 to 2025). "To investigate the biological role of FOXP1 in the hematologic tumor cells, we performed loss-of-function experiments in the THP1 cells." (PMID 40672953, 2025). "FOXP1 expression was associated with distinct TME characteristics across various blood cancer types." (PMID 40672953, 2025). "An important factor regulating the MHC-II expression in some blood cancers is Forkhead box P1 (FOXP1)." (PMID 33499042, 2021). "In most hematological tumors, FOXP1 expression demonstrated a positive correlation with the expression levels of stimulatory immune genes such as ICOSLG, IL2RA, and HMGB1, and a negative correlation with the expression levels of inhibitory immune genes, such as SLAMF7." (PMID 40672953, 2025).
hematologic cancers (2 papers, 2025). "This study systematically analyzed the association of FOXP1 expression with clinical outcomes, including prognosis and immunotherapeutic response, as well as biological functions across a range of hematological cancers." (PMID 40672953, 2025).
nervous system disorder (2 papers, 2018 to 2020). A non-neoplastic or neoplastic disorder that affects the brain, spinal cord, or peripheral nerves. "Failing to activate de novo gene expression can cause neurological disorders as was shown for the Foxp1 transcription factor." (PMID 29674952, 2018).
genetic disorder (1 paper, 2025). "FOXP1 syndrome is a rare genetic disorder caused by heterozygous sequence variants in — or deletions of — the FOXP1 gene." (PMID 40066139, 2025).
myopathy (1 paper, 2021). A disease of the muscle in which the muscle fibers do not function properly. "We therefore further determined whether HDACs are necessary for FoxP1 to induce skeletal muscle wasting and myopathy." (PMID 33527776, 2021).
FOXP1 also shares sentences with these, for which no sentence is quoted: gastric MALT lymphoma (4 papers); immune disorders (3); anxiety disorder (2); attention deficit-hyperactivity disorder (2); Barrett esophagus (2); bipolar disorder (2); esophageal squamous cell carcinoma (2); head and neck cancer (2); Insulin resistance (2); lupus (2); Lynch syndrome (2); MALT lymphoma of the thyroid (2); metastatic melanoma (2); myeloid leukemia (2); thyroid (2); 3-methylglutaconic aciduria type 1 (1); ADNP syndrome (1); airway hyperresponsiveness (1); allergic respiratory disease (1); alopecia (1); Angelman syndrome (1); Anorexia (1); Anosmia (1); aortic valve atresia (1); arteriopathy (1); asthma (1); atrioventricular septal defect (1); atypical ductal hyperplasia (1); bacterial infection (1); Bamforth-Lazarus syndrome (1).
A further 80 diseases each share a sentence with FOXP1 in 1 paper.